FGF2 (fibroblast growth factor 2)
Diseases named in the same sentence as FGF2 in open-access papers (continued):
Sharing a sentence is not in itself a finding about the gene and the disease.
tumor (continued). "For now, it is well established that VEGF, FGF-2, and ANG-2 upregulate MT1-MMP, MMP-2, and MMP-9 expression: consistently, a positive correlation has been observed between the levels of these angiogenic factors and those of MT1-MMP, MMP-2 or MMP-9 in tumor tissues." (PMID 39120324, 2024). "TAMs promote tumor angiogenesis by secreting a plethora of pro-angiogenic growth factors, cytokines, and chemokines that induce EC proliferation and migration, including EGF, FGF-2/bFGF, platelet-activating factor (PAF), PDGF, VEGF, TNF-α, IL-1, IL-8/CXCL8, and CCL18." (PMID 38580870, 2024). "Tumor cells orchestrate the recruitment and activation of stromal cells within the TME and release inflammatory and pro-fibrotic factors, including TGF-B, PDGF, and fibroblast growth factor-2 (FGF-2), amongst others, inducing differentiation of stromal cells into CAFs." (PMID 39057155, 2024). "FGF2, FGF7 and FGF10, as members of the fibroblast growth factor family, are involved in various biological processes, including embryonic development, cell growth, tissue repair, tumor growth and invasion, and have been reported to be critical targets in the fibrosis process." (PMID 37275903, 2023). "Third, PGF is able to upregulate the expression of fibroblast growth factor (FGF-2), platelet-derived growth factor (PDGF-β), and matrix metalloproteinases (MMPs), by periendothelial fibroblasts, smooth muscle cells, or inflammatory cells in tumor stroma as well." (PMID 37508400, 2023). "FGFR1 and FGFR3 expression was determined via IHC on the primary patient tumour, PDXs and PDXOs and very low expression of FGFR1 and FGFR3 were noted in those with high FGFR2c expression confirming that the FGF2/FGFR2c autocrine loop is the target of BGJ398 in these models." (PMID 38062117, 2023). "Similarly, other factors released by tumor cells, such as the platelet-derived growth factor (PDGF) and fibroblast growth factor 2 (FGF-2), or inflammatory signals such as interleukin (IL)-1, IL-6 and tumor necrosis factor alpha (TNF-α), recruit and proliferate additional CAFs." (PMID 37173977, 2023). "On the contrary, M2 macrophages promote tumor cell proliferation, distant metastasis, drug resistance, and angiogenesis and suppress immunity, which is stimulated by IL-10, transforming growth factor beta (TGF-β), and neovascularization agents VEGF and fibroblast growth factor-2 (FGF-2)." (PMID 35958625, 2022). "FGF-2 overexpression facilitated tumor cell growth without changing migration ability." (PMID 35439170, 2022). "MSCs play an important role in promoting tumour angiogenesis through the release of high levels of cytokines and pro-angiogenic growth factors, including vascular endothelial growth factor (VEGF), fibroblast growth factor-2 (FGF-2), IL-8, IL-6, angiopoietin, and transforming growth factor-β (TGF-β)." (PMID 36338118, 2022). "It is important to note that FGF-2 promotes endothelial cell migration in vitro, increases VEGF synthesis and induces the synthesis of collagen, fibronectin and proteoglycans by endothelial cells, reinforcing both tumor angiogenesis and the desmoplastic reaction in PDAC tumors." (PMID 34503252, 2021). "Interestingly, another transcription repressor DACH1, known to mediate a negative FGF signaling feedback loop through FGF2 repression, showed ≥ 15-fold specific overexpression in the F2↑ tumor." (PMID 33853673, 2021). "Moreover, we observed significantly lower microvessel density in CXCL13-overexpressing 4T1 tumor, and this was supported by one previous study that CXCL13 modulated angiogenesis by inhibiting fibroblast growth factor 2-induced chemotaxis, proliferation, and survival of endothelial cells." (PMID 35693216, 2021). "FGF2 and FGF19, seem to be involved in maintaining cancer stem-like cells (CSCs) with CD44High/CD133High cell membrane markers, which play a central role in the tumor microenvironment, potentially enhancing HCC tumorigenesis, metastasis, and anticancer drug resistance." (PMID 33802841, 2021).
tumor (continued). "Additionally, MET, TGFα, FGF2, CD151, and MMP3 are some of the oncogenic targets of miR-152 in human cancers; by targeting these genes, miR-152 leads to inhibition of cell proliferation and tumor metastasis." (PMID 33680048, 2020). "The high expression of FGF2 was related to the tumor size (p = 0.026), gender (p = 0.047), and lymph metastasis (p = 0.007), while the expression of FGF2 was not correlated with the race, age, tumor site, and pathological stage of ESCC cases and so on (p > 0.05)." (PMID 33381388, 2020). "Very recently, FGF2 is found to be inhibited by the PI3K/Akt signaling pathway, which implies that the PI3K/Akt pathway and FGF2 might be potential therapeutic targets to treat tumor recurrence." (PMID 32210363, 2020). "Reduction in HIF-1α and expression of angiogenic factors (FGF2, PDGF-AA, CYR61, and VEGF) and subsequently intratumor hypoxia is due to the ability of Infigratinib/Bevacizumab to increase tumor oxygen supply via Infigratinib-induced vascular normalization of tumor blood vessels." (PMID 33321903, 2020). "The anti-FGF2 antibody itself did not affect tumour growth in unirradiated mice." (PMID 32792542, 2020). "Studies reveal that, for tumor development and metastasis to occur, angiogenesis in the tumors must involve an interplay of some or all these growth factors- VEGF, interleukin 8 (IL-8), basic fibroblast growth factor (bFGF/FGF-2), and matrix metalloproteinases (MMPs)." (PMID 32489466, 2020). "Furthermore, some studies found that the expression of FGF2 was detected in tumor stroma rather than tumor parenchyma." (PMID 33425737, 2020). "In addition, our findings indicated that stromal FGF2 rescues BET inhibitor effects in metastatic UM cells and also showed upregulation of FGFR expression as an adaptive response to BET inhibitors in cell lines and patient tumor samples." (PMID 30610113, 2019). "In contrast, weak affinity was detected between PSS and VEGF165, while the KD of heparin was 8.09 × 10−7 M. As FGF2 is a crucial growth factor to regulate angiogenesis and the function of tumor cells, these data indicate that FGF2 was probably a potential target for PSS to improve tumor environment." (PMID 31035725, 2019). "Furthermore, regular subcutaneous injections of FGF2 also decreased or prevented xenograft tumor growth in mice without noticeable toxicity." (PMID 30422399, 2019). "To better understand the effects of targeting angiogenic factors in the tumor, we built a new tissue-based systems biology model characterizing the extracellular network that involves four main angiogenic factors regulating tumor angiogenesis, including VEGF, FGF2, TSP1, and PF4." (PMID 31379588, 2019). "In Sonic Hedgehog (SHH) MB, the crosstalk between basic fibroblast growth factor (bFGF/FGF2) activated fibroblast growth factor (FGF)-receptor (FGFR) and tumor growth factor receptor beta (TGF-β) signaling determines the migratory and the invasive capabilities of the tumor cells." (PMID 31835472, 2019). "In addition, BET inhibitors could enhance FGFR expression in UM cell lines and patient tumor samples, while FGFR inhibitors (AZD4547 and BLU9931) reversed the effects of stromal FGF2." (PMID 31167513, 2019). "The role of extracellular AGR2 (eAGR2) is particularly interesting because it enhances tumor angiogenesis and the invasion of vascular endothelial cells and fibroblasts by interaction with vascular endothelial growth factor (VEGF) and fibroblast growth factor 2 (FGF2)." (PMID 29937991, 2018). "The anti-angiogenic/anti-tumor activity of PTX3 was not restricted to FGF2." (PMID 30349543, 2018). "In addition, FGF2 acts as a survival factor that inhibits tumor cell apoptosis by an autocrine secretion-signaling loop." (PMID 28722655, 2017).
tumor (continued). "In conclusion, targeting the MAPK signal transduction pathway through the targeting of FGF9, FGF2, MECOM, PRKACB and PLA2G4C might increase tumor responsiveness to irinotecan and improve patient survival thus being therapeutically and prognostic significant in CRC patients." (PMID 28749961, 2017). "To investigate the molecular determinants of the different angiogenic patterns, we studied the expression of various genes involved in the control of tumor angiogenesis but no relevant variations (data not shown) were observed for several of these (FGF2, PECAM1, MCAM, COX2)." (PMID 28903354, 2017). "Therefore, FGF2 signalling seems less efficient in KO/PyMT than in WT/PyMT cells, and KO/PyMT tumour cells appear to have deficits in HSPG-dependent, but not HSPG-independent, mitogenic signalling." (PMID 28102194, 2017). "After testing a number of different culture conditions it was shown that CTCs could be propagated in vitro only if they were cultured in hypoxic conditions, as tumor spheres in serum-free media supplemented with epidermal growth factor (EGF), B27 and basic fibroblast growth factor (FGF2)." (PMID 27457474, 2016). "Hence, the observed reductions of TGFβ, FGF2, IL-6 and HGF can not only be due to the reduction of tumor-infiltrating CAFs but also due to quantitative and/or qualitative changes in other intratumoral cell populations such as reduced numbers of ECs due to an anti-angiogenic effect of the treatments." (PMID 25849942, 2015). "On the other hand, the expression of FGF2, as well as CXCR4, CD45 and COL1A1, in the isolated fibrocyte-like cells was similar between the tumours, suggesting that the increase of FGF2 in bevacizumab-treated tumours was due to the increase in the number of these cells." (PMID 26635184, 2015). "On this basis, given the prominent role of FGF2 in tumor progression and metastatic activity of these cells [26 and references therein], we investigated whether the anti-metastatic potential of CDV could be extended also to these virus-independent tumor cells." (PMID 25609197, 2015). "Interestingly, 24 h after tasquinimod exposure, mRNA expression of different angiogenic factors (Vegfc, Nrp-1, Fgf2, Il-6) was decreased in MCH-IIhigh macrophages compared to vehicle TAMs, suggesting that M1 macrophages contribute to tumor vasculature shrinkage." (PMID 26673090, 2015). "BP1 can also support tumor growth and angiogenesis of FGF-2 expressing non-tumorigenic SW-13 cells." (PMID 25429350, 2014). "Thus, since BP1 is a soluble carrier protein that can bind FGF-2 molecules available in solution, it might also release FGF-2 molecules from HSPGs located on the cell surface of tumor vascular endothelial cells." (PMID 25429350, 2014). "Interestingly, MCs induce tumor development and progression angiogenesis-mediated by means of the release of various angiogenic molecules such as Vascular Endothelial Growth Factor (VEGF), Fibroblast Growth Factor-2 (FGF-2), tryptase, chymase." (PMID 25056597, 2014). "The possible mechanism is that angiogenesis in the tumor may be driven by additional factors, such as fibroblast growth factor 1 (FGF-1), FGF-2, transforming growth factor-β (TGF-β), platelet-derived endothelial cell growth factor (PD-ECGF), and placental growth factor (PIGF)." (PMID 23799045, 2013). "Even without expression of ectopic FGFR1, these cells could undergo FGF2-induced EMT, suggesting that if FGF was present in the tissue microenvironment in vivo, the tumours from which these cell lines were established may have expressed an FGFR-dependent EMT phenotype." (PMID 22701738, 2012). "The VEGF, FGF2 and PDGF produced by vascular endothelial cells are proposed to be involved in the activation of lymphatic endothelial cells, which in turn produce matrix metalloproteases and urokinase plasminogen activator (uPA) that can promote malignant tumor growth." (PMID 21399234, 2011). "In addition to VEGF, FGF-2, ANG-2, HIF-2α, and PDGFC are also involved in tumor angiogenesis." (PMID 21843314, 2011).
tumor (continued). "Besides, the effect of estrogen can be accounted for by alterations in different growth factors: VEGF, and FGF-2, even though increases in such growth factors do not necessarily imply their strict requirement for tumor development." (PMID 17222350, 2007). "In lung cancer cell lines with the FGF2/FGFR1 pathway, targeting this resistance mechanism with EGFR-specific TKI does not significantly increase apoptosis, indicating that FGFR inhibitors may stabilize tumor progression rather than cause tumor regression." (PMID 39544292, 2024). "Furthermore, when we quantified the levels of FGF2 in tbLCM, to our surprise, we did not observe any significant difference in the levels of soluble FGF2 in lung conditioned media from tumor bearing (tbLCM) mice as compared to tumor naïve mice." (PMID 38581619, 2024). "Additionally, FGF2/FGFR signaling changes are prevalent in various tumor types, with FGF2 being overexpressed in advanced malignant tumors, FGFR2 inhibitors playing a crucial role in tumor growth and progression, and overcoming anticancer drug resistance through novel extracellular inhibitors." (PMID 38139837, 2023). "Moreover, the worse prognosis of the patients with FGF2 levels’ decrease might be related to angiogenesis inhibition that is not “per se” sufficient to halt tumor progression." (PMID 32456056, 2020). "Viewed in the context of the results of our earlier studies, these data suggest that the tumor phenotype may be due to the promotion of FGF-2 responsiveness by the Akt3/IWS1 pathway and the induction of EMT and stem cell self-renewal by FGF-2 via the FGF-2/KDM2B/miR-101/EZH2 pathway." (PMID 28515962, 2017). "While these results were obtained using kidney tubule cells, it is intriguing to speculate that the heparanase-FGF2 axis plays an important role in cancer spread due to the well established connection between FGF2 and EMT in a variety of other situations, including tumor cells." (PMID 25105093, 2014). "It is widely recognized that mast cells induce neovascularization and angiogenesis by secreting VEGF, FGF-2, PDGF, and IL-6 to the tumor stroma in addition to nonclassical pro-angiogenic drivers such as proteases, particularly tryptases and chymases." (PMID 39858015, 2025). "Tumour associated macrophages is another kind of non-tumour stromal cells, that support tumour growth and immune evasion by secreting factors such as TGF-β, VEGF, FGF-2, and various matrix metalloproteinases (MMPs)." (PMID 40852716, 2025). "FGF2/FGFR1 induces resistance to radiotherapy in GBM, and inhibition of FGFR1 reduces radioresistance in GBM mouse xenografts, although tumor growth is not reduced by FGFR1 silencing alone without irradiation." (PMID 39682716, 2024). "After cell straining and centrifugation, cell suspensions consisting of tumor cells and various non-neoplastic stromal cells, were transferred to uncoated culture flasks after which EGF/FGF2 supplemented medium was added." (PMID 36269546, 2022). "Moreover, an ELISA showed that FGF-2, which is secreted by CAFs,12 was present in B16-F10 tumour lysates but not in lysates or conditioned medium of B16-F10 cells cultured in vitro, suggesting that CAFs in the tumour stroma are functional in terms of FGF-2 production." (PMID 33299131, 2021). "This suggests that the FGF2‐FGFR continuous activation of the downstream network signal pathway through bypass and the growth of the tumor cells is not restricted by the inhibitory effect of EGFR‐TKI." (PMID 32163227, 2020). "Interestingly, the switch in the expression levels of FGF1 and FGF2 (downregulated and upregulated in low-responder cells, respectively) as well as the upregulation of one member of the PDGF family (i.e. PDGFD) might be potentially driving the tumor progression in these GBM low-responder cells." (PMID 34316686, 2020).
tumor (continued). "Thus, IM activates the FGF-2/FGFR autocrine loop in various IM-resistant GIST cell lines and this mechanism might have a negative impact on the disease progression due to the activation of tumor cell migration, invasion, and enrichment of tumors with stem-like cell (SC) properties." (PMID 32599808, 2020). "The therapeutic efficacy of this combination regimen was indistinguishable between FGF-2− and FGF-2+ fibrosarcomas (approximate 80% tumor suppression in both models)." (PMID 32709869, 2020). "To validate these findings in genetic tumor models, we took a pharmacological gain-of-function approach in which FGF-2 negative (FGF-2-) tumors were grown in a Matrigel containing recombinant FGF-2 protein." (PMID 29423271, 2018). "In support of this possibility we found that, unlike FGF2, effects of the acidic FGF1 (pI≈6) on tumour cell proliferation were not affected by α3(V) ablation and that FGF1 did not bind α3(V)-NTD or GPC1 in immunoprecipitations." (PMID 28102194, 2017). "Collectively, these results demonstrate that under hypoxic conditions, HIF-1β expression regulates the expression of various tumor growth-related factors, namely EGF, HGF, and VEGF, but not FGF2." (PMID 25068796, 2014). "Collectively, these data suggest that under hypoxic conditions, HIF-1β expression regulates the expression of tumor growth-related factors, namely EGF and HGF, but not FGF2." (PMID 25068796, 2014). "A previous immunoblot analysis showed no expression of FGF2 by HL cell lines KM-H2 and L428, although the same study did detect FGF2 expression in primary HRS cells from HL tumor biopsy samples." (PMID 23988031, 2013). "Inhibition of the NF-κB pathway by using tetrathiomolybdate, a specific copper chelator, or by transfecting a dominant-negative IκBα vector reduced the secretion of VEGF, fibroblast growth factor 2 (FGF2), IL-1α, IL-6, and IL-8 in vitro and SUM149 tumor growth and angiogenesis in vivo." (PMID 32883032, 2020). "In the FGF-2+ tumors, anti-VEGF treatment did not inhibit tumor angiogenesis." (PMID 32709869, 2020). "However, in MM, despite being a nonsolid tumor, intensive neovascularization occurs, which results in the release of cytokines such as vascular endothelial growth factor (VEGF) and fibroblast growth factor-2 (FGF-2)." (PMID 32679860, 2020). "The role of NRP1 as a coreceptor for FGFs in (tumor) vasculature is still unclear, as NRP1 may bind several FGFs but does not affect the FGF-2-induced proliferation of HUVECs." (PMID 30717262, 2019). "Similarly, despite MM being a non-solid tumour situated in the BM, blood vessel development is increased through secretion of cytokines such as vascular endothelial growth factor (VEGF) and fibroblast growth factor-2 (FGF-2)." (PMID 29662010, 2018). "Besides, we performed the ELISA with the supernatants from the tumor cells treated with HA + DOX to rule out that the addition of HA had affected the interaction between the heparan sulfate proteoglycans and FGF-2, and releasing it into the cell medium." (PMID 30564299, 2018). "By instead culturing the cells in FGF-2 (no EGF) we show that the amplification was retained at passage 15 and thus constitute an appropriate model system to study EGFR-amplified pediatric GBM tumor cells." (PMID 28148893, 2017). "While previous studies showed contradictory results whether FGF-BP enhances the anti-apoptotic effects of FGF-2 or is not related to apoptosis, we clearly demonstrate in this paper the anti-apoptotic function of human FGF-BP in tumor cells." (PMID 22111880, 2011). "Given the fact that macrophages did not express FGFRs and that FGF-2 stimulation did not alter macrophage migration, we hypothesized that FGF-2 indirectly activates macrophages via fibroblasts or pericytes for tumor cell migration." (PMID 35439170, 2022).